ATG5 (autophagy related 5)
Diseases named in the same sentence as ATG5 in open-access papers (continued):
Sharing a sentence is not in itself a finding about the gene and the disease.
Autoimmunity (9 papers, 2012 to 2021). The occurrence of an immune reaction against the organism's own cells or tissues. "The direct association between ATG5 and autoimmunity was identified in hypothesis-free genome-wide association study (GWAS) data." (PMID 30386331, 2018). "Several research groups have implicated the role of ATG5, ATG7, and ATG16L1 in keratinocytes, melanocytes, and immune cells in autoimmunity and cancer." (PMID 29988591, 2018). "Recent studies have revealed the role of autophagy and CNS autoimmunity, in which ATG5 might play an important role." (PMID 30386331, 2018). "In this focused review, we discuss the latest insights into the role of ATG5 in autoimmunity." (PMID 30386331, 2018). "A contribution of the autophagic processes to autoimmunity is consistent with the deficient or impaired functions of ATG5 (and other components of non-canonical autophagy) in SLE, but the mechanism for this relationship is unclear." (PMID 28424695, 2017). "Polymorphisms in atg5 have recently been linked with SLE64, 65, raising the possibility that disruption of the regulatory mechanism we describe may contribute to autoimmunity in human disease." (PMID 26965188, 2016). "The autoimmunity and inflammation associated with SLE may be caused by loss of other ATG5-dependent effects, such as regulation of IFN and proinflammatory cytokine secretion, clearance of dying cells, and dendritic cell antigen presentation." (PMID 21994884, 2012). "Interestingly, in mice, the lack of ATG5-dependent negative thymic selection generates autoimmunity and multiorgan inflammation." (PMID 21994884, 2012).
Cognitive impairment (9 papers, 2019 to 2026). Abnormal cognition is characterized by deficits in thinking, reasoning, or remembering. "Another study elucidates that plasma ATG5 level is increased and positively correlated with cognition impairment in Alzheimer’s patients." (PMID 38511768, 2024). "This study found that serum ATG5 level was positively correlated with incidence and deterioration of cognition impairment in stroke patients." (PMID 38511768, 2024). "In conclusion, serum ATG5 level not only correlated with Th2 and Th17 cells, but also exhibited a predictive value for the incidence and deterioration of cognition impairment in stroke patients." (PMID 38511768, 2024). "Together with the pathogenic role of autophagy and mitophagy in the onset and progression of cognitive disorders, our results also highlight the role of ATG5 and Parkin as potential biological markers of cognitive impairment." (PMID 31882960, 2019). "In addition, other clinical studies indicate that serum ATG5 level is related to cognition impairment." (PMID 38511768, 2024). "Thereby, further studies are required to validate that the correlation of ATG5 with Th2 and Th17 cells could impact cognitive decline in stroke patients by eliminating the influence of other ATGs on promoting cognition impairment." (PMID 38511768, 2024). "Thus, it was assumed that the estimating value of ATG5 for cognition impairment was due to its positive correlation with Th17 cells." (PMID 38511768, 2024). "However, the role of serum ATG5 level in estimating cognition impairment in stroke patients is unclear." (PMID 38511768, 2024). "This study aimed to explore the correlation of serum ATG5 with CD4+ T cells and cognition impairment in stroke patients." (PMID 38511768, 2024). "Accordingly, previous findings showed lower values of ATG5 in serum/plasma samples of AD, mild cognitive impairment (MCI), mixed dementia, and PD subjects, and a downward trend of ATG5 concentrations in the temporal cortex of AD and DLB patients compared to those in CTRL subjects." (PMID 38256197, 2024). "Hence, this study quantified serum ATG5 level and the CD4+ T-cell subset, aiming to investigate their inner correlation and their linkage with cognition impairment incidence and deterioration in stroke patients." (PMID 38511768, 2024). "Serum ATG5 level was elevated in stroke patients with cognition impairment compared to those without (P=0.037)." (PMID 38511768, 2024). "Next, to clarify whether ATG5 and ATG12 levels are related to clinically overt dementia, we examined ATG5 and ATG12 plasma levels in mild cognitive impairment (MCI) and dementia patients as well as in control subjects without dementia." (PMID 30894637, 2019). "Our findings suggest that IF intervention significantly attenuated HFD-induced cognitive impairment and neuroinflammation, increased BDNF levels, improved histological alterations, decreased Beclin-1 and p62 immunohistochemical expression, and upregulated LC3 and ATG5 mRNA expression." (PMID 42185381, 2026). "Comparisons of autophagy-related gene 5 (ATG5) level and CD4+ T-cell subset between patients with and without cognition impairment." (PMID 38511768, 2024).
COVID-19 (9 papers, 2021 to 2026). A disease caused by infection with severe acute respiratory syndrome coronavirus 2. "We next assessed the levels of key autophagy markers p62, LC3, ATG5, and beclin-1 in the blood of healthy controls and COVID-19 patients at admission and one week later." (PMID 37174682, 2023). "In the present study, we combined the ex vivo and in vitro approaches to further examine the connection between inflammatory mediators and autophagy markers LC3, ATG5, and p62 in COVID-19." (PMID 37174682, 2023). "Plasma ACBP concentrations positively correlated with ATG 3, ATG5 and LC3II, but negatively correlated with ATG4B, BECN1 and galectin 8 in participants with COVID-19." (PMID 39835130, 2024). "Unlike p62, the circulating levels of LC3 and ATG5, both involved in autophagosome formation, were not significantly altered in COVID-19 patients in our study, although a tendency towards LC3 increase was observed." (PMID 37174682, 2023). "It was found that transcript levels of key factors promoting autophagy, i.e. ULK-1, ATG5, UVRAG, AMBRA, PIK3C3, and LC3, are significantly reduced in mononuclear cells of COVID-19 patients compared to healthy controls, and the phenomenon was more pronounced in severe COVID-19 patients." (PMID 33692788, 2021).
non-small cell lung carcinoma (9 papers, 2019 to 2025). A group of at least three distinct histological types of lung cancer, including non-small cell squamous cell carcinoma, adenocarcinoma, and large cell carcinoma. "TECPR1, identified in the carcinoma group, is associated with downregulating autophagy-related gene 5 (ATG5) when expressed at low levels in non-small cell lung cancer, suppressing autophagy and enhancing cell viability." (PMID 40446009, 2025). "Furthermore, when ATG5 knockdown inhibits CAFs autophagy, invasion of non-small cell lung cancer cells can be repressed." (PMID 37000314, 2023). "Furthermore, in non-small cell lung cancer, cell invasion can be inhibited dramatically when CAFs autophagy is repressed by silencing of ATG5." (PMID 37000314, 2023). "Moreover, there is also an association between SNPs in ATG5 and ATG7 with clear cell renal cell carcinoma and variants of ATG5 and ATG10 have been linked to non-small cell lung cancer." (PMID 33147747, 2020). "The m6A methyltransferase METTL13 positively regulates autophagic flux by upregulating the expression of LC3B, ATG5, and ATG7 and plays a key role in β-elemene reversal of gefitinib resistance in non-small cell lung cancer." (PMID 36263177, 2022). "Upregulation of GATA6, a transcription factor that mediates the expression of autophagy-related genes such as ATG5, ATG7, and ATG12 by erlotinib treatment promotes treatment resistance in cellular models of non-small cell lung cancer (NSCLC)." (PMID 32245178, 2020). "Moreover, in the non-small cell lung cancer (NSCLC) mouse model, Atg5 tissue-specific depletion promoted tumor initiation through a mechanism dependent on Treg recruitment to the TME." (PMID 33335860, 2020).
thyroid cancer (9 papers, 2014 to 2025). "The results indicate that patients carrying the ATG5 single nucleotide polymorphisms rs2245214 have a higher probability to develop thyroid carcinoma (OR 1.85 (95% CI 1.04–3.23), P = 0.042)." (PMID 24739953, 2014). "In conclusion, genetic variation in ATG5, a central player in the autophagy process, is found to be associated with increased susceptibility for thyroid carcinoma, indicating a role for autophagy in thyroid carcinogenesis." (PMID 24739953, 2014). "The second purpose of this study was to see whether MIEAP or ATG5 KO causes the oncocytic phenotype in BRAFV600E–derived thyroid cancers." (PMID 36187114, 2022). "To investigate the impact of LINC00162 knockdown and sorafenib treatment on autophagy in thyroid cancer cells, we analyzed the expression levels of ATG5, ATG7, and MAP1LC3B genes in B-CPAP cancer cells." (PMID 40804316, 2025). "To better understand the role of LINC00162 in thyroid cancer progression, we evaluated the expression of the autophagy-related genes ATG5, ATG7, and MAP1LC3B." (PMID 40804316, 2025). "In conclusion, the authors propose that MIEAP and ATG5 function as critical tumor suppressors in BRAFV600E-driven thyroid cancer by maintaining cellular integrity through distinct but complementary mechanisms." (PMID 39874138, 2025). "In conclusion, we here show that MIEAP or ATG5 KO accelerates the development of thyroid cancers in a mouse model of BRAFV600E–mediated thyroid cancer." (PMID 36187114, 2022). "Future research may focus on therapeutic strategies to enhance MIEAP and ATG5 function or mimic their actions, potentially offering a novel approach for treating aggressive thyroid cancers." (PMID 39874138, 2025). "Five hundred and sixty-seven miRNAs associated with nine autophagy proteins (ULK1, ATG16L1, MAP1LC3B, PRKAA1, ATG12, ATG 14, ATG5, mTOR and BECN1) were identified, of which sixty-two are accompanied by thyroid cancer, and only miR-125b is associated with the autophagy modulation in this pathology." (PMID 36980957, 2023). "While Atg5 downregulation did not protect thyroid cancer cells from the lethal effects of Obatoclax treatment, shAtg7 reduced the number of dying cells by approximately 50%." (PMID 27144341, 2016). "In conclusion, we here show that MIEAP and ATG5 are both tumor suppressors in thyroid carcinogenesis, but as we have anticipated from our previous data, KO of either molecule does not confer the oncocytic phenotype to BRAFV600E-positive thyroid cancers." (PMID 36187114, 2022).
acute myeloid leukemia (8 papers, 2016 to 2026). Acute myeloid leukemia (AML) is a group of neoplasms arising from precursor cells committed to the myeloid cell-line differentiation. "Conversely, in acute myeloid leukemia (AML), monoallelic loss of a key autophagy gene Atg5 is sufficient to accelerate the disease progression and aggressiveness in a mouse AML model." (PMID 37886168, 2023). "LncRNA SNHG5 stabilized autophagy related 5 (ATG5) mRNA and induced cancer-associated fibroblasts-like phenotype by interaction with PTBP1 in acute myeloid leukemia cells." (PMID 40790019, 2025). "This study discovered that CELF1 specifically binds to the mRNA of ATG5, a critical gene involved in autophagy regulation, and promotes its expression in ADR-resistant acute myeloid leukemia (AML) cells." (PMID 40781108, 2025). "Lower expression of key ATGs (BECN1, ATG3, ATG5, ATG4, ATG14) was shown in a large panel of primary acute myeloblastic leukemia (AML) patients as compared to normal granulocytes." (PMID 37887330, 2023). "Autophagy-related proteins such as ULK1, ATG3, ATG5, ATG13, and ATG14 were markedly expressed in various acute myeloid leukemias when comparing the microarray-based expression profiling of distinct ATG proteins from human AML samples with the human normal hematopoiesis." (PMID 37180758, 2023). "In acute myeloid leukemia (AML), SNHG5 interacts with PTBP1, stabilizing ATG5 mRNA and inducing autophagy in mesenchymal stromal cells (MSCs), which in turn acquire a cancer-associated fibroblast (CAF)-like phenotype, ultimately enhancing chemoresistance." (PMID 41550840, 2026).
Ataxia (8 papers, 2015 to 2025). Ataxia refers to impaired coordination of voluntary muscle movement. "Loss of ATG5 leads to ataxia in humans and flies, yet the underlying cellular pathway involved remains elusive." (PMID 39815080, 2025). "In this study, we generated two homozygous C. elegans strains with mutations (E121D and E121A) at positions corresponding to the human ATG5 ataxia mutation to investigate the effects of ATG5 mutations on autophagy and motility." (PMID 37334197, 2023). "A pathogenic ATG5 E122D mutation leading to human spinocerebellar ataxia reduces both the interaction with ATG12 and autophagy induction." (PMID 37334197, 2023). "In summary, we introduced an ATG5 mutation associated with human spinocerebellar ataxia intoC. elegansfor the first time and demonstrated that this mutation causes locomotor defects in the nematode." (PMID 37334197, 2023). "Specifically, the loss-of-function mutation in the human autophagy-related gene 5 (ATG5) at E122D has been linked to the pathogenesis of spinocerebellar ataxia in humans." (PMID 37334197, 2023). "ATG5-related SCAR25 is another recessively inherited ataxia recently attributed to mutations in a core autophagy component in a single family." (PMID 34130600, 2022). "Here we identified a novel mutation in a core autophagy gene, ATG5, in two children with ataxia, and demonstrate a reduction in autophagic response, also reproducing the phenotype in yeast and fly models." (PMID 26812546, 2016). "In summary, we demonstrate that the homozygous E122D mutation of ATG5, a unique mutation found in two human subjects with ataxia, results in reduced conjugation to ATG12 and in an overall decrease in autophagy activity." (PMID 26812546, 2016). "Collectively, these results indicate that the E121 mutation on ATG-5 reduced the locomotion ability of worms that might be related to the human spinocerebellar ataxia." (PMID 37334197, 2023). "To further characterize the effect of the E122D mutation on the development of ataxia, we generated Drosophila melanogaster knockouts for Atg5, and reconstituted the Atg5-null mutant flies with transgenes expressing wild-type (WT) or E122D human ATG5." (PMID 26812546, 2016). "The neuronal Atg5 and Atg7 knockouts present with behavioral deficits and progressive motor dysfunction, such as ataxia." (PMID 25875846, 2015). "Along similar lines, recent findings in milder autophagy disorders with phenotypes limited to specific organ systems have stimulated the investigation of tissue‐specific pathomechanisms in autophagy disorders, for example, ATG7‐related NDDs or ATG5‐related ataxia." (PMID 39420677, 2025). "This hypothesis is in agreement with previously characterized mouse models, in which neuron-specific knockout of Atg5 results in ataxia-like phenotypes." (PMID 26812546, 2016). "It is perhaps not a surprise after all that a mutation that affects ATG5 might be behind childhood ataxia." (PMID 26929993, 2016).
cutaneous melanoma (8 papers, 2015 to 2025). A primary melanoma arising from atypical melanocytes in the skin. "We demonstrate that higher Sec23a and Atg5 expression levels appear to be protective factors and favorable diagnostic (TNM staging) and prognostic (overall survival) markers for skin cutaneous melanoma (SKCM) and colon adenocarcinoma (COAD) patients." (PMID 32811814, 2020). "Sec23a and Atg5 expression level were both significantly lower in skin cutaneous melanoma (SKCM) patients with advanced primary tumors and regional lymph node metastasis in comparison with SKCM patients of early stages." (PMID 32811814, 2020).
depression (8 papers, 2022 to 2025). "Upregulated ATG5 expressions are associated with depression status in RLS." (PMID 39776356, 2025). "Therefore, we aimed to investigate the expression and diagnostic potential of ATG3 and ATG5, as well as the relationships between these proteins and laboratory markers, depression, disease score, quality of life, and sleep in RLS patients." (PMID 39776356, 2025). "Additionally, the correlation analyses demonstrated that ATG3 was significantly correlated with the quality of sleep, while ATG5 was associated with the quality of life and depression status." (PMID 39776356, 2025). "Conversely, reducing ATG5 expression in neurons was able to alleviate this pathology and improve depression-like behavior in mice." (PMID 40497971, 2025). "Relationship of ATG3 and ATG5 with quality of life and sleep, the depression and laboratory markers in patients with restless legs syndrome." (PMID 39776356, 2025). "ATG3 was substantially correlated with the quality of sleep, whereas ATG5 was correlated with the quality of life and depression status (p < 0.05)." (PMID 39776356, 2025). "The present results indicated that ATG3 was substantially correlated with the quality of sleep, whereas ATG5 was correlated with the quality of life and depression status." (PMID 39776356, 2025). "To explore the effects of hyperactive autophagy in DG neurons on neuronal BDNF, AHN, and depression-like behaviors, we knocked down Atg5 expression in the hippocampal DG neurons of CORT mice using AAV-hSyn-miR30-shRNA (Atg5)." (PMID 36793868, 2023). "In a corticosterone (CORT)-induced depression model, excessive neuronal autophagy activity was observed in the DG region of the brain, upregulating the expression of ATG5." (PMID 38026940, 2023). "Furthermore, there was a positive correlation found between depression levels and serum ATG5 concentrations." (PMID 39776356, 2025). "Furthermore, the correlation analyses indicated that ATG3 was substantially correlated with the quality of sleep, whereas ATG5 was correlated with the quality of life and depression status." (PMID 39776356, 2025). "In a CORT-induced depression model, it was found that increasing the expression of ATG5 could lead to overactive neuronal autophagy, which would lead to the significant degradation of BDNF, thus hindering the conversion of NSCs to mature neurons." (PMID 40497971, 2025). "Additionally, reduced Atg5 expression was observed in ApoE4 mice and an LPS‐induced depression mouse model, delineating the impairment in ApoE4 mice upon stress stimulation." (PMID 38506067, 2024). "However, suppression of ATG5 in neurons alleviated these pathological phenomena, leading to an improvement in depression-like behavior in mice." (PMID 38026940, 2023). "Similar results were also seen in the CSDS-induced mouse model of depression, where the expression of autophagy-related proteins such as LC3-II/I, Beclin-1, ATG5, and ATG7 was significantly decreased in the hippocampus after 10 days of stress exposure." (PMID 40497971, 2025). "OSA patients with neuropsychiatric symptoms, such as depression, fatigue, sleepiness, headache, and memory impairment, had higher LC3B/ATG5 expression and lower DNA methylation levels over the promoter regions of these two genes." (PMID 36805797, 2023). "The expression of autophagy‐related genes (Atg5, Atg7, Atg12, Becn1, Mmp9, Fkbp5, and Map1lc3b), which are reported to be upregulated in the brains of MDD patients, were examined in the hippocampus and midbrain of control and depression model mice." (PMID 39715728, 2025).